EGFR (epidermal growth factor receptor)
Diseases named in the same sentence as EGFR in open-access papers (continued):
Sharing a sentence is not in itself a finding about the gene and the disease.
tumor (continued). "In this study, we observed that KPS, BM at the time of initial diagnosis, BM progression after TKI, EGFR mutation type, uncontrolled primary tumor and the number of BM were the independent prognostic factors for OS in real-world practice." (PMID 37020869, 2023). "It has been shown that tumor-associated macrophages (TAMs) can promote CSC phenotypes in mouse models of cancer by acting on the epidermal growth factor receptor (EGFR)/signal transducer and activator of transcription 3 (STAT3)/sex-determining region." (PMID 36675306, 2023). "Molecular testing of needle biopsy or surgically resected tumor tissue is the "gold standard" for diagnosing EGFR mutation status." (PMID 37014500, 2023). "It detects the mutation of tumor driver genes EGFR and KRAS and the expression of drug resistance proteins ERCC1 and RRM1, respectively." (PMID 37854320, 2023). "In view of the aberrant expression of HER3 and/or activation of HER3 and its ligand, NRG1 is associated with tumor progression and acquired resistance to EGFR and HER2-targeted therapies, and HER3 emerges as an interesting target." (PMID 37947595, 2023). "The EGFR gene encodes a protein that stimulates molecular pathways that allow the growth and development of the tumor microenvironment." (PMID 38322283, 2023). "The anti-tumor effect of PD-1 inhibitors has also been demonstrated in preclinical models with EGFR mutations." (PMID 37869096, 2023). "Contrariwise, the EGFR mutation was significantly associated with MRI concerning the occurrence of greater tumor (22.38 ± 21.35 cm3 versus 7.68 ± 6.44 cm3, p = 0.046) and edema volume (72.44 ± 60.71 cm3 versus 31.92 cm3, p = 0.028)." (PMID 37240478, 2023). "All patients underwent colonoscopy and acquired tumor lesion samples were further analyzed for programmed death-ligand 1 (PD-L1), epidermal growth factor receptor (EGFR) expression, deficient mismatch repair (dMMR), and microsatellite instability (MSI) status." (PMID 36802389, 2023). "For example, erlotinib and gefitinib are tyrosine kinase inhibitors (TKIs) that target tumor cells with activating mutations in the epidermal growth factor receptor (EGFR) gene." (PMID 37631304, 2023). "Since combination treatment can promote the efficacy of immunotherapy by increasing both tumor mutation burden (TMB) and tumor antigen exposure, combination therapy has become one of the major research trends for EGFR‐TKI‐resistant patients." (PMID 37723846, 2023). "We also found that EGFR mutation was a prognostic factor for tumor control and that prior craniotomy was correlated to overall survival." (PMID 36676186, 2023). "Radiation can cause abnormal expression of various genes in tumor cells, including epidermal growth factor receptor (EGFR)." (PMID 36909247, 2023). "Next-generation sequencing (NGS) is commonly used to test the EGFR mutational status on tumor samples, but it is expensive and requires time and trained staff for both experimental procedures and result interpretation." (PMID 37958668, 2023). "MET, ERBB2, VEGFR2, PFGFR, and EGFR, among others, represent acknowledged targets of semaphorins often associated with tumor progression or poor prognosis." (PMID 38067240, 2023). "They found a discordance of primary EGFR mutation positivity between tumour tissue and ctDNA, with up to 10% of patients testing negative for EGFR mutation in tissue, having an EGFR mutation identified on ctDNA." (PMID 37476385, 2023). "NSCLC tumors with EGFR mutations generally have low PD-L1 expression levels, but EGFR can also be an intrinsic mechanism, causing the tumor to express high levels of PD-L1." (PMID 36672698, 2023). "Both Ki-67 and EGFR mutations are involved in the proliferation and regulation of tumor cells, and both are independent factors affecting the prognosis of patients." (PMID 37390230, 2023). "This patient's tumor exhibited 40% PD‐L1 expression and an activating L858R short variant mutation in EGFR." (PMID 35747993, 2023).
tumor (continued). "TAMs are an important cellular source of EGF secretion in tumour tissue and have been found to be significantly associated with epidermal growth factor receptor (EGFR) expression in tumour cells and poor prognosis." (PMID 38143746, 2023). "While genetic mutations within EGFR or other cancer driver pathways mediated mechanisms are well-documented, the role of tumor cell and tumor immune microenvironment in mediating the response to osimertinib remains elusive." (PMID 36817465, 2023). "Four months prior to the admission, he had been diagnosed with unresectable adenocarcinoma (clinical stage IIIA/T4N1M0; an activating EGFR-mutation [L858R]-positive; proportion of tumor expressing PD-L1, 50–74%) originating from the right lower lobe." (PMID 39516993, 2023). "C1 differed from C2 in several key markers, including cell cycle activity, tumor stage, mutation profile, prognosis, and responses to immune- and anti-EGFR therapies." (PMID 37903125, 2023). "Mutations in KRAS resulted in sustained activation of the protein it encoded, so that even if upstream EGFR overexpression is blocked, downstream events cannot be regulated, and tumor growth and proliferation continue." (PMID 37880688, 2023). "Further investigations examined tumor genotyping with liquid biopsy and demonstrated a decline in mutated clones upon EGFR blockade withdrawal." (PMID 38201553, 2023). "In patients with tumours harbouring a common mutation of the EGFR gene, adjuvant osimertinib therapy was associated with a large improvement in both DFS and overall survival (OS)." (PMID 37999109, 2023). "Then we investigated the mechanisms underlying the tumor-suppressive effects of activated PKG I. The localization of EGFR and PKG I was visualized by confocal laser scanning microscopy." (PMID 36653376, 2023). "EGFR gene mutation is capable of positively regulating the expression of PD-L1 in tumor cells; EGFR-TKI can negatively regulate the expression of PD-L1 by inhibiting the nuclear factor-κB (NF-κB) signaling pathway." (PMID 37895255, 2023). "A genomic study showed that transformed SCLC tumour samples retain the original EGFR-activating mutation detected at the baseline biopsy sample." (PMID 37376053, 2023). "These three parameters all point to the same conclusion, the pathologic regression rates in surgical specimens following NA-ChRT were reduced if an EGFR mutation was present in the tumor." (PMID 37751214, 2023). "How to further improve the anti-tumor activity of patients with EGFR mutations is currently a key issue." (PMID 37089959, 2023). "One well-researched tumor-specific antigen is EGFRvIII, a mutant variant of EGFR that remains active and is found exclusively in 25–30% of GBM cases." (PMID 38002496, 2023). "Liquid biopsy can identify the resistance to targeted therapy in a timely manner, showing a higher coverage of tumor heterogeneity, more complex resistance patterns, and some new resistance mutation sites, such as EGFR p.V769M and KRAS p.A11V." (PMID 36835972, 2023). "Molecular detection of tumor tissues obtained by biopsy or surgical resection is the gold standard for identifying EGFR mutations." (PMID 38094613, 2023). "Subsequently, these T cells can specifically recognize and lyse tumor cells harboring these EGFR mutations, achieving a potent and specific anti-tumor response." (PMID 37766136, 2023). "A multi-center phase II study also reported the promising anti-tumor efficacy of toripalimab plus chemotherapy in NSCLC patients with EGFR mutations." (PMID 37147602, 2023). "Unlike classic EGFR mutations, there are few studies investigating tumor genomic features and their clinical implications for EGFR 20ins." (PMID 37308490, 2023). "The comparison between exosome-derived and tumor-derived mutations showed a sensitivity of 100% in detecting EGFR mutations and a specificity greater than 96%." (PMID 36768828, 2023).
tumor (continued). "With the emergence of KRAS and BRAF mutations, resistance to EGFR-targeted therapy has developed, driven by mechanisms affecting both cellular pathways and the tumor microenvironment." (PMID 37762323, 2023). "On the other hand, gefitinib works similarly to erlotinib by selectively targeting the mutated EGFR protein in tumor cells." (PMID 37901797, 2023). "EGFRvIII is a tumour-specific splice variant of EGFR in which amino acids 6–273 of the extracellular domain are deleted, resulting in constitutive receptor activity." (PMID 36829563, 2023). "EGFR-tyrosine kinase inhibitors (TKI) such as gefitinib target EGFR for antitumor effects, but EGFR mutations (Such as T790M or S492R mutations) are an important cause of tumor cell generation." (PMID 36770689, 2023). "All the results revealed that the EGFR pathway-related prognostic gene signature was linked with various malignant pathways and tumor malignant behaviors." (PMID 37759950, 2023). "In 2004, the correlation between NSCLC tumor sensitivity to gefitinib and mutations in the EGFR tyrosine kinase domain was discovered." (PMID 38201251, 2023). "Histopathological findings revealed ALK‐negative, EGFR L858R mutation‐positive invasive adenocarcinoma with a PD‐L1 tumor proportion score of less than 1%." (PMID 36605695, 2023). "Analysis of the corresponding mutations in the ctDNA NGS data revealed good concordance with tumor sample, the same mutation variant of EGFR was found in all paired CSF and tumor tissue samples." (PMID 36937524, 2023). "The disruption of proper EGFR signaling and trafficking leads to diseases like cancer, where overexpression or activating mutations within EGFR promote tumor growth." (PMID 37752992, 2023). "Overexpression of the EGFR (epidermal growth factor receptor) gene is associated with higher tumor aggressiveness, decreased survival rate, and a higher number of metastases." (PMID 37895255, 2023). "The serum proteomic classifier established was examined for EGFR gene mutation status and verified in an independent validation cohort, demonstrating high concordance and sensitivity with tumor biopsies." (PMID 36902280, 2023). "First, due to the deficiency of original data, we failed to incorporate some potential prognostic factors (e.g., tumor cell differentiation, EGFR mutation, ALK-EML4 fusion) in variable analysis." (PMID 37318606, 2023). "Coexistence of CD10 and EGFR overexpression was found in 25% of cases and was associated with age (P=0.008), tumor size (P=0.030) and hitologic types (P=0.014)." (PMID 38974258, 2023). "The cost-effectiveness of using LB in the care pathway is particularly indicated in patients with EGFR-mutated tumours." (PMID 35532791, 2023). "RAS mutational status and tumor sidedness impact the efficacy of bevacizumab and EGFR inhibitors in the first-line setting." (PMID 37409250, 2023). "For instance, there is a need to explore how AhR knockdown or pharmacological inhibition would affect PM2.5 induced tumor promotion in lung AT2 cells with EGFR driver mutations and to compare the impact of PM2.5 with high or low PAH content on these responses." (PMID 37696458, 2023). "In this study, we proposed a deep learning-based approach to assess the personalized probability of tumor progression in patients who had advanced NSCLC with EGFR mutations treated with EGFR-TKIs." (PMID 36670497, 2023). "Overexpression and mutation of the epidermal growth factor receptor (EGFR) are associated with tumor development." (PMID 37280663, 2023). "They demonstrated that the HBP rescued the cell surface expression of specific glycoproteins, including epidermal growth factor receptor (EGFR), in the glucose-deficient tumor microenvironment." (PMID 37880766, 2023). "Surprisingly, inactivation of some of the strongest tumor suppressors in the presence of oncogenic KRAS variants decreased tumor growth in the presence of oncogenic EGFR." (PMID 37828026, 2023).
tumor (continued). "In ESCC treatment, tumor-associated targets applied clinically are rare but have included EGFR, VEGF, HER-2 and PD-L1." (PMID 37817249, 2023). "The selection of targeted therapy depends on the RAS mutational status of the tumor as anti-EGFR antibodies are only approved for patients with RAS wild-type tumors." (PMID 37774394, 2023). "In conclusion, the results of this study indicated that NSCLC patients harboring EGFR‐plasma mutations have poorer outcomes compared to those with tumor‐only mutations during EGFR TKI therapies." (PMID 34427045, 2022). "We observed VEGF up-regulation on EGFR-mutated tumor cells, and more importantly, EGFR is also expressed on tumor-associated endothelial cells." (PMID 36313314, 2022). "A complex model combining serum tumor makers and CT features is more accurate in predicting EGFR mutation status in NSCLC patients than using either serum variables or imaging features alone." (PMID 35422977, 2022). "Clinically, EGFR T790M mutation detected in tumor tissues is a gold standard, but it is difficult to obtain tissue samples at some times." (PMID 36776375, 2022). "EGFR is implicated in tumor development, progression, and metastasis, via downstream signaling cascades involving AKT, MEK, and ERK." (PMID 35416106, 2022). "Exon 19 deletion and exon 21 L858R point mutation are regarded as two separate entities, resulting in different structural changes in EGFR, differences in the rate of concomitant mutations, and differences in the overall tumor mutation burden." (PMID 35599308, 2022). "The assessed patient characteristics in this study included sex, age, smoking status, epidermal growth factor receptor (EGFR) mutation, PD-L1 expression level, survival status, tumor, node, and metastasis (TNM) stage, and metastasis locations." (PMID 35646945, 2022). "EGFR is a receptor whose over‐expression in cancer cells is linked to cell proliferation, angiogenesis, and tumor metastasis." (PMID 35079631, 2022). "Previous studies have implicated tumor suppressor NDRG1 in mediating iron chelation mechanism of action through the inhibition as EGFR, TGF-β, and STAT3." (PMID 36213122, 2022). "The cluster of patients with advanced-stage, high tumor grade, and positive EGFR expression represent patients at high risk of distant metastasis." (PMID 36188649, 2022). "Here, we analyzed the role of UTX in NSCLC in association with the widely recognized tumor driver epidermal growth factor receptor (EGFR)." (PMID 34661759, 2022). "The tumor heterogeneity was attributed to both genetic and non‐genetic mechanisms acting at various intervals for targeted drugs, including EGFR‐TKIs in NSCLC patients with EGFR mutations." (PMID 35029047, 2022). "Paradoxically, patients with EGFR mutations are reported to have lower PD‐L1 expression and tumor mutational burden (TMB), leading to poor response to anti‐PD‐1/PD‐L1 inhibitors." (PMID 34958168, 2022). "As to tumor heterogeneity, the deep learning score of EGFR mutation provides a non-invasive method for identifying NSCLC patients sensitive to EGFR tyrosine kinase inhibitors or immune checkpoint inhibitors treatments." (PMID 36176388, 2022). "EGFR overexpression activates pathways related to proliferation, angiogenesis, cell motility, metastasis, and other tumor-related processes, and the EGFR pathways associated with cell growth are RAS–RAF–MEK–ERK MAPK and AKT–PI3K–mTOR." (PMID 35565451, 2022). "The invasiveness of this procedure—and inability to obtain samples from some patients—led test makers to work on diagnostics capable of identifying EGFR gene mutations in plasma samples through the detection of circulating tumor DNA." (PMID 36360466, 2022).
tumor (continued). "A previous study evaluated the feasibility of using ctDNA in blood samples as a substitute for tumor biopsy to determine EGFR mutation status and further linked EGFR mutation in ctDNA to prognosis." (PMID 35057806, 2022). "All the cases of EGFR mutations can be detected in the tumor tissues (n = 31) along with six additional mutations." (PMID 35651679, 2022). "Approximately half or more NSCLC patients with EGFR mutations who develop resistance to the first- and second-generation EGFR-tyrosine kinase inhibitors (TKI) will develop a secondary EGFR T790M mutation in the tumor." (PMID 36387176, 2022). "Based on data analysis of 9649 Chinese primary NSCLC patients, we calculated the exact proportion of EGFR subtypes in NSCLC and evaluated the TMB level, PD-L1 expression level and tumor immune microenvironment among different EGFR mutation subtypes." (PMID 35265073, 2022). "EGFR signaling pathway activity is associated with tumor cell proliferation, angiogenesis, tumor invasion, metastasis, and inhibition of apoptosis." (PMID 35105871, 2022). "Since deep learning is an end-to-end prediction model that learns abstract mappings between tumor images and EGFR mutation status, it is important to explain the prediction process so that users can gain confidence in the prediction process." (PMID 36119545, 2022). "It is interesting to note that the frequency of EGFR mutations in these SNSCC tumours is distinct from NSCLC, where Ex20ins are rare, while the Ex19del and L858R mutations predominate." (PMID 35053553, 2022). "Hypoxia is a hallmark of many tumours and it leads to overexpression of various proteins such as EGFR." (PMID 35702041, 2022). "There were significant differences between the EGFR mutation rate and the sex, smoking history, pulmonary nodule morphology, patients with cavity sign, hair prick sign, thymus depression sign and tumor with vascular convergence sign groups of LUAD patients." (PMID 36685887, 2022). "In this line, Osimertinib has recently been approved for use as adjuvant therapy after complete tumor resection in patients with stage IB-IIIA NSCLC with epidermal growth factor receptor (EGFR) exon 19 deletions or exon 21 L858R mutations." (PMID 36430262, 2022). "It was caused by decreased dependency on EGFR signaling, related to increased tumor heterogeneity, such as increased TMB and EMT." (PMID 35029047, 2022). "Further, the integration of postoperative factors (.Ki‐67, EGFR mutation, and tumor differentiation) and Model 2 greatly improved the predictive accuracy (AUC: 0.962 in the training set and 0.942 in the validation set, p < 0.001)." (PMID 35289087, 2022). "More recently, it has been demonstrated that T-cell-mediated anti-tumor immunity can be rescued by suppressing the EGFR/CD73 axis in EGFR-mutated NSCLC." (PMID 35563517, 2022). "Activation of epidermal growth factor receptor (EGFR) by overexpression or mutation has been observed in a variety of human cancers, including BCa, which results in tumor cell proliferation, invasion, migration, and evasion of apoptosis." (PMID 36230734, 2022). "CTCs share some characteristics with the primary tumor, such as mutations and gene expression signatures (e.g., EGFR)." (PMID 35330158, 2022). "For this experiment, we removed the exon 20 insertion mutants to keep a heterogeneous tumor model comprised primarily of TKI-sensitive EGFR variants." (PMID 35304574, 2022). "On the other hand, the 50-year-old patient (P36) had NSCLC with bone metastasis and carried composite EGFR mutations, namely p.E746_A750del/p.L861R, had received 2 months of erlotinib therapy, during which he showed a 63% tumor regression." (PMID 36011410, 2022).